TNF (tumor necrosis factor)
Diseases named in the same sentence as TNF in open-access papers (continued):
Sharing a sentence is not in itself a finding about the gene and the disease.
tumor (continued). "Specifically, TAS-115 alone and in combination with DOXO significantly reduced the levels of key pro-inflammatory cytokines, including TNF-α, IL-1α, and IL-6, which are often elevated in the TME and contribute to tumor progression, therapy resistance, and immunosuppression." (PMID 41289612, 2025). "Likewise, in the flank tumor model, neutralization of IFN-γ and TNF-α resulted in a significant reduction of CCL3 and CCL4 by CD8+ T cells in the tumor bed of LLCova-bearing mice." (PMID 40553564, 2025). "In TNBC, the interactions between molecules or co-regulatory networks, such as NF-κB may simultaneously participate in the regulation of MMP9 and TNFα, while JAK2 may form cross-pathways with PI3K/Akt, jointly affecting tumor progression." (PMID 40356970, 2025). "For TNF-α, our previous work and other studies have demonstrated that EMT confers cetuximab resistance; the EMT transcriptional factor Snail induces TNF-α that promotes tumor-related inflammation and boosts EMT." (PMID 41205596, 2025). "Tumor-derived PGE2 induces the nuclear accumulation of p50 NF-κB in M-MDSCs, diverting their response to IFN-γ towards immunosuppression by upregulating NO production and reducing TNF-α expression." (PMID 39990210, 2025). "A well-defined ratio of CD4 + and CD8 + T cells, such as a 1:1 ratio, has been shown to enhance efficacy by combining the direct tumour-killing ability of CD8 + T cells with the cytokine support provided by CD4 + T cells, particularly Th1-skewed cells that secrete IFN-γ, IL-2, and TNF-α." (PMID 40624498, 2025). "Th1 cells, activated by IFN-α/β and IL-12, promote tumor suppression via IFN-γ and TNF-α." (PMID 41007256, 2025). "Some strains, such as Clostridium acetobutylicum DSM792, have been modified to express therapeutic chemicals, such as tumor necrosis factor (TNF-α) and interleukin-2 (IL-2), which further enhance anti-tumor immunity and have direct lethal effects in the tumor microenvironment by inducing T cells." (PMID 40141809, 2025). "Further, we co‐cultured LLC tumor cells with peritoneal macrophages at ratios of 1:1 and 3:1, stimulating them with CCM or CFM, respectively, and measured the expression levels of CD86, CD206, TNF‐α, and CXCL10." (PMID 40637137, 2025). "Interestingly, histone deacetylase 6 (HDAC6) inhibition, suppressed transforming growth factor beta (TGF-β)/SRY-BOX2 (SOX2) and EMT pathway through tumor necrosis factor alpha (TNF-α) activation, and polarized macrophages from pro- to anti-tumor phenotypes." (PMID 40470218, 2025). "Additionally, SiGel@SN38/aOX40 treatment resulted in the highest proportions of CD4+ and CD8+ T cells, accompanied by elevated serum and tumor levels of IFN-γ and TNF-α compared to other groups." (PMID 40176815, 2025). "Given that TNF EVs promote EMT in MCF-7 cells, we hypothesized that TNF EVs might also drive the acquisition of a tumor stem cell-like phenotype." (PMID 40567500, 2025). "The synergistic increase in TNF‐α in the ZGE + DOX group may reflect enhanced immune activation or stress signaling, potentially contributing to tumor suppression via inflammatory‐mediated apoptosis or immune recruitment." (PMID 41306344, 2025). "However, exposure to paclitaxel increased tumor growth and volume, which were reversed by ibuprofen that significantly modulated cytokine levels, suppressing MCP-1 and increasing TNF-α, IL-2, VEGF, and MMP-9." (PMID 40924302, 2025). "Additionally, specific interactions, such as interactions with various TME cells via TNF-TNFRSF1B signaling and interactions with myeloid cells via the TNF-TNFRSF1A complex, were exclusively observed in relapsed tumor samples." (PMID 40876452, 2025).
tumor (continued). "Similarly, fungal dysbiosis in GC, including enrichment of Apiotrichum and Cutaneotrichosporon, drives inflammation through cytokines such as TNF-α and CXCL9, which suppress tumor-suppressive miRNAs and promote oncogenic pathways." (PMID 39973938, 2025). "Cholesterol can induce PD-1 expression, impede CD8+T cell proliferation, and diminish levels of toxic cytokines (such as TNF-α, IFN-γ) by amplifying endoplasmic reticulum stress, thereby fostering immune evasion by tumor cells and functional impairment of CD8+T cells." (PMID 40169575, 2025). "In addition, elevated expressions of antitumor factors such as IFN-γ and TNF-a, as well as decreased expression of tumor promoting factors such as IL-10 and TGF-β were detected in the tumor tissues of SEMA7A-knockdown LLC tumor-bearing mice." (PMID 41019072, 2025). "Thus, investigating how TNF-α and HMGCR regulate the tumor microenvironment and downstream inflammatory reactions is crucial for understanding tumor progression mechanisms and identifying novel therapeutic targets." (PMID 41450917, 2025). "Flow cytometry analysis revealed an increase in the proliferative (Ki67+), activated (CD69+), and cytotoxic (TNFα+, IFNγ+, GzmB+) CD8+ and CD4+ T cells in tumor tissues and spleens of GL261 tumor-bearing mice treated with cinobufagin, compared to the vehicle-treated group." (PMID 39901195, 2025). "On the other hand, type I interferons (IFN-α/β) significantly promote TANs polarization toward an anti-tumor phenotype by activating the Fas/FasL pathway, inducing apoptosis-related genes in pro-tumor TANs, and upregulating effector molecules such as NO, H2O2, and TNF." (PMID 40568594, 2025). "Hence, this study chose to assess serum concentrations of TNF‐α, IL‐2, IL‐10, MMP‐9, and VEGF‐C to reflect the conditions of the tumor microenvironment before metastasis." (PMID 40808216, 2025). "Moreover, in PDAC patients, TNF-α induces epithelial–mesenchymal transition (EMT), which facilitates development of stroma within the tumor." (PMID 40136652, 2025). "Tumor-derived EVs bearing heat shock protein 70 (HSP70) promote migratory and cytolytic activities of natural killer (NK) cells and increase tumor necrosis factor-alpha (TNF-α) production in macrophages, thus creating an immune-stimulatory environment and providing anti-tumor immunity." (PMID 40182121, 2025). "Second, our study was cross-sectional—we measured TNF-α and tumor markers at a single time point (diagnosis) and did not track patient outcomes in this report." (PMID 40299527, 2025). "However, it did enhance anti-tumor T-cell responses, increasing the presence of PD-1+ CD62Llow CD4+ and CD8+ T-cells and the production of PRF1, TNF-α, and IFN-γ." (PMID 40281554, 2025). "During the process of in vitro expansion and repetitive stimulation, along with the high concentrations of inhibitory cytokines in the tumor microenvironment, CAR-T cells develop an exhausted phenotype (upregulation of PD-1, LAG3, TIM3, and TIGIT and decreased secretion of IL-2, TNF-α, and IFN-γ)." (PMID 40002679, 2025). "TNF‐α, while capable of inducing apoptosis via mTOR inhibition, paradoxically enhances cell survival and proliferation through NF‐κB and MAPK activation, creating a tumor‐promoting inflammatory state." (PMID 40387523, 2025). "In addition to TNF and NF-κB, we also investigated the role of MAP3K8, also known as Cot or Tumor Progression Locus 2 (TLP2)." (PMID 40431657, 2025). "In our study, we observed a slight increase in the expression of IL-17A, IL-6, and CXCL13 following PD-1 signaling activation, and no inhibitory effect on IFN-γ and TNF-α, which are downregulated in tumor T cells." (PMID 40825269, 2025).
tumor (continued). "The hallmark cytokines of Th1 cells, including interferon-gamma (IFN-γ) and tumor necrosis factor-alpha (TNF-α), facilitate macrophage activation, upregulate major histocompatibility complex (MHC) expression on tumor cells, and potentiate CTL-mediated cytotoxicity." (PMID 40860882, 2025). "Mechanistically, Dectin-1 activation in myeloid cells leaded to increased production of pro-inflammatory cytokines such as IL-12 and TNF-α, which in turn promoted the recruitment and activation of effector T cells within the TME, thereby amplifying anti-tumor immunity." (PMID 41163402, 2025). "Detection of killer cytokines IFNG/IFN-γ, TNF/TNF-α, and GZMB secreted by CD8+ T cells revealed that reduced circGRAMD4 expression relieved tumor cell-induced immunosuppression, whereas increased circGRAMD4 expression suppressed the production or release of these immune factors." (PMID 40373256, 2025). "Additionally, it has been demonstrated that MSCs stimulate tumor angiogenesis by releasing bFGF, VEGF, FGF-2, IL-8, IL-6, IGF-1, TNF, and TGF β." (PMID 39974358, 2025). "By inhibiting TNF-induced MMP9 expression, GOS can hinder tumor spread." (PMID 40002373, 2025). "Furthermore, L-NIL treatment preserved the capacity of CAR T cells to kill tumor cells and produce the effector cytokines IFN-g and TNF-a." (PMID 40235478, 2025). "Additionally, TNF is essential for establishing antitumor immune responses by facilitating dendritic cell maturation, CD8+ T‐cell activation, and tumor infiltration." (PMID 40297580, 2025). "Th1 cells primarily produce IFN-γ and TNF-α, which activate other immune cells, including CD8+ T cells, macrophages, and B cells, and promote cell-mediated immune responses and sustain anti-tumor activity." (PMID 40458394, 2025). "Additionally, Ccn1‐KO tumors demonstrated significantly higher protein levels of TNFα, IL2, and IFNγ in tumor and serum." (PMID 40287974, 2025). "Activated CD8+ T cells exert their cytotoxic effects through multiple mechanisms, including the secretion of anti-tumor cytokines such as IFN-γ and TNF-α, the release of cytotoxic mediators such as perforins and granzymes, or the direct killing of tumor cells via the FASL-FAS signaling pathway." (PMID 41182407, 2025). "Furthermore, B7-H3 upregulation increased the production of Th1/Th2 cytokines (including TNF-α, IL-2, IL-4, IFN-γ, IL-6, and IL-10) in the TME and triggered TNF-α secretion in CRC cells, contributing to tumor growth." (PMID 40214484, 2025). "Following target tumor cell recognition, activated CAR-T cells release cytokines such as IFN-γ and GM-CSF, which in turn activate monocytes to secrete large quantities of IL-6, TNF-α, IL-1β, and CCL2." (PMID 41219641, 2025). "Here, TNFα signalling, response to cytokine stimulus, actin filament‐based process and immune response, regulation of MAPK cascades and cell adhesion were specific for AD, SQ, NET and MT tumours." (PMID 39995112, 2025). "Similarly, we detect increased IFN-γ, TNF-α, and IL-2 expression in CD4+ T cells after coculture with RCOR2-KO tumor cells." (PMID 40608411, 2025). "When overstimulated, however, this pathway stimulates proliferation of tumor cells via nuclear factor NF‐κB/JNK/ERK signaling, thereby inducing the production of cytokines, such as TNF, IL‐1α, and IL‐6, which act in a positive feedback loop to promote tumor growth." (PMID 40922674, 2025). "Furthermore, treatment of anti-IFN-g enhanced CAR T cell expansion in cocultures with imMac and preserved the ability of CAR T cells to lyse tumor cells and produce IFN-g and TNF-a." (PMID 40235478, 2025). "Additionally, CAFs can inhibit the secretion of cytokines such as TNF-α and IFN-γ and cytotoxic granules containing perforin and granulase B by NK cells, suggesting tumor-promoting effects of CAFs on NK cells." (PMID 40805183, 2025).
tumor (continued). "TNF-α is pleiotropic in cancer but chronically activates NF-κB and AP-1 programs that support proliferation, invasion, and EMT, with context-dependent crosstalk that can tip inflammation toward tumor promotion." (PMID 41440526, 2025). "Furthermore, osthole increases the tumor-infiltrating CD4+/CD8+ T cell ratio and elevates serum levels of IL-2 and TNF-α, while concurrently reducing the population of splenic regulatory Tregs." (PMID 40495147, 2025). "Tumor cells may express PD-L1 constitutively or in response to inflammatory cytokines, such as IFN-γ and TNF-α, within the TME." (PMID 40963596, 2025). "Additionally, lymphocytes can inhibit tumor cell growth and improve the prognosis of patients with malignant tumors via secreting IFN-g and TNF." (PMID 39512498, 2025). "In vivo, in the tumor microenvironment, TNFR2+ and TNF+ Tregs expanded in parallel." (PMID 40977146, 2025). "Additionally, tumor-secreted VEGF, transforming growth factor β (TGFβ), tumor necrosis factor α (TNFα) and CCL2 can induce lung angiogenesis and trigger local inflammation." (PMID 40370456, 2025). "In addition, although tumor‐infiltrating CD4+, CD8+, and γδ T cells all showed high expression of IFN‐γ and TNF‐α in both groups with immunotherapy, the frequency of TNF‐α+ γδ T cells was markedly higher when transferred cells were loaded with antigen." (PMID 40091603, 2025). "Furthermore, we isolated the peritumor- and tumor-infiltrating M2 macrophages, and found that M2 macrophages in peritumor secreted significantly higher of IL-10 and lower levels of IFN-g and TNF-α, compared with that in tumor using Multiplex assay." (PMID 40756343, 2025). "Inflammatory cytokines such as TNF-α and IL-6 have been shown to upregulate histone demethylases, including Jmjd3 (KDM6B), which affects the expression of genes, leading to stem-like, therapy-resistant tumour phenotypes." (PMID 40647494, 2025). "In this study, we demonstrate that exosomes derived from PCa cells contribute to CD8+ T cell exhaustion via upregulating PD-1 and TIM-3 and perturbing the secretion of effector cytokines, such as IL-2, IFN-γ, TNF-α, and TGF-β, thereby reducing the tumor-killing ability of CD8+ T cells." (PMID 40681951, 2025). "Their activity against tumor-specific antigens was then determined with tetrazolium (MTT), chromium-51 (51Cr) release, or cell counting kit 8 (CCK8) assays, or by measuring cytokine levels (IFN-γ, TNFα, IL-2) with ELISA." (PMID 40700119, 2025). "The palonosetron administration also induced the reduction in circulating cortisol and TNF-α levels, along with the increase in IFN-γ levels, indicating that palonosetron not only directly inhibits tumor growth but also modulates systemic inflammatory and immune responses." (PMID 41155333, 2025). "Moreover, cytokines secreted by TAM M2, including TNF-α, ICAM-1, and IL-6, further contribute to tumor growth and invasion." (PMID 40299539, 2025). "Among the proteomic markers, elevated levels of serum ceruloplasmin, MYO1B, salivary CPLANE1, serum albumin, HSP 27, gamma actin, SCC 1, and A4, serum SNCG and SCCAg and immune cell markers such as, IL‐6, TNF‐α, and CD4 + T cell were suitable proteomic tumor markers in detecting OSCC." (PMID 40256126, 2025). "Chronic inflammation contributes to local tumor growth through sustained cytokine signaling (IL-6, TNF-α), fibroblast activation, and angiogenesis, but does not necessarily drive metastasis." (PMID 41374930, 2025). "In non-pathological settings, modest levels of TNF-a are expressed in response to threats such as pathogens or tumor cell growth and serve to activate and direct microglia to eliminate the threat via proinflammatory pathways of the TNFR1." (PMID 39860337, 2025). "Notably, TNF-alpha signaling via NF-κB and IL6/JAK/STAT3 signaling have been widely characterized to foster an inflammatory tumor microenvironment that favors metastasis." (PMID 39489818, 2025).
tumor (continued). "The drawback is that this article did not to investigate how anti-PD-L1 therapy regulates tumor blood vessels via TNF-α." (PMID 40370455, 2025). "TNFα and IL-1 inhibit osteogenic differentiation of OS cells by activating the ERK signaling pathway, thereby maintaining an undifferentiated state that facilitates tumor progression and metastasis." (PMID 40895569, 2025). "Notably, however, the frequency of TNF-α, and IFN-γ producing T cells was increased for ABE-TILs upon co-culture with autologous tumor lines naturally expressing TIGIT or TIM3-specific ligands (i.e., CD112 and CD155 and galectin-9, respectively)." (PMID 41394272, 2025). "However, the serum TNF-α increased 15–25 times by the LLC tumor compared to that of the control group; the treatment of low or high doses of DTT water extract reduced serum TNF-α specifically by 27% and 39%, respectively." (PMID 41226740, 2025). "For instance, it has been established that pro-inflammatory cytokines such as IL-2, IFNs, and TNF-α are possessed with a greater repute for cell-mediated immunity activation, for example, through CTL and NK cell activation which leads to tumor growth inhibition." (PMID 40309351, 2025). "Mechanistically, perivascular Tenascin C produced by tumor cells activates TLR4-dependent perivascular macrophages within pre-metastatic niches, resulting in upregulated expression of NO and TNF to induce endothelial cells-mediated production of niche components." (PMID 41417432, 2025). "Effector T cells, primarily CD8+ cytotoxic T lymphocytes (CTLs) and CD4+ helper T cells, are critical for directly targeting and eliminating tumor cells through the release of cytokines such as IFN-γ, TNF-α, and IL-2, and the use of cytotoxic granules containing perforin and granzymes." (PMID 40475782, 2025). "Interestingly, both tumor‐derived CD4+ and CD8+ T cells produce considerably more TNF‐α and IFN‐γ than those in the PB." (PMID 40498413, 2025). "Furthermore, the MMW + α-PD-L1 combination therapy promoted polarization toward anti-tumor M1-type macrophages, which secreted elevated levels of effector molecules, including IFN-γ, TNF-α, IL-6, and IL-12p70." (PMID 41383334, 2025). "The expression level of TNF was positively correlated with the infiltration abundance of CD8 + T Cell, CD4 + T Cell, Neutrophil, and Dendritic Cell, but negatively correlated with tumor purity." (PMID 41287122, 2025). "CD4+ Th1 cells secrete IFN-γ and TNF-α to trigger CD8+ T and NK cells to eliminate tumor cells." (PMID 39782693, 2025). "In terms of tissue invasion and distant metastasis, TAMs enhance the invasiveness and migratory capacity of tumor cells by activating the EMT, particularly through the activation of toll-like receptor-4 and the subsequent secretion of cytokines such as IL-6 and TNF-α." (PMID 40098971, 2025). "High polyamine levels in CRC also impair anti-tumor immune responses by reducing the expression of adhesion molecules, such as CD44 and LFA-1, as well as by decreasing the production of key cytokines, such as IFN-γ and TNF." (PMID 40927726, 2025). "Notably, exosomal ligands like PD-L1, TNF, FasL, and TRAIL, which bind to receptors on tumor cells, are being explored as potential tools for cancer therapy." (PMID 39961904, 2025). "Furthermore, the tumour-promoting TF Runx3 previously shown to be upregulated in TAMs was downregulated by SFV/Luc and SFV/TNFα." (PMID 40547518, 2025). "Additionally, inflammatory cytokines like interleukin-6 (IL-6) and tumor necrosis factor-alpha (TNF-α), released by both the tumor and the immune response, contribute to increased clot formation." (PMID 39857281, 2025). "In addition, these neutrophils produce inflammatory cytokines such as TNF-α and IFN-γ, which boost the immune response and support eliminating tumor cells through programmed cell death (apoptosis)." (PMID 41009604, 2025).